PCSK9 (proprotein convertase subtilisin/kexin type 9)
Diseases named in the same sentence as PCSK9 in open-access papers (continued):
Sharing a sentence is not in itself a finding about the gene and the disease.
prostate adenocarcinoma (2 papers, 2024). "In addition, we demonstrated that BLCA (P < 0.001), KIRC (P = 0.01), KIRP (P = 0.001), prostate adenocarcinoma (PRAD) (P = 0.034), and SKCM (P = 0.004) patients with higher expression of PCSK9 have a shorter DSS." (PMID 38600469, 2024).
rectal cancer (2 papers, 2024 to 2025). A primary or metastatic malignant neoplasm that affects the rectum. "Reduced expression of PCSK9 and LDL mediated by PCSK9 was associated with a decreased risk of EC, GC, and rectal cancer." (PMID 40443776, 2025). "Based on the HEIDI results, there was heterogeneity in the association between blood PCSK9 and rectal cancer (p = 0.01)." (PMID 40443776, 2025). "Decreased expression of PCSK9 in blood was associated with a reduced risk of rectal cancer (OR = 0.65, 95% CI: 0.45–0.95, p = 0.03), but an increased risk of pancreatic head cancer (OR = 3.11, 95% CI: 1.01–9.52, p = 0.046)." (PMID 40443776, 2025). "PCSK9‐mediated LDL was negatively associated with rectal cancer (OR = 0.70, 95% CI: 0.52–0.96, p = 0.03)." (PMID 40443776, 2025). "Additionally, PCSK9‐mediated LDL was negatively associated with rectal cancer (OR = 0.60, 95% CI: 0.48–0.75, p < 0.01), while NPC1L1‐mediated LDL was positively associated with rectal cancer (OR = 4.57, 95% CI: 2.10–9.95, p < 0.01)." (PMID 40443776, 2025).
renal dysfunction (2 papers, 2020). "Lipid parameters and statin treatment have excellent correlation with PCSK9 levels in patients without renal dysfunction." (PMID 31963408, 2020).
renal failure (2 papers, 2016 to 2021). "PCSK9 levels decreased by 74.2%, 79.8%, and 67.9% in mild, moderate, and severe renal insufficiency, while it decreased by 68.1% in patients with normal renal insufficiency." (PMID 34462692, 2021).
rhabdomyolysis (2 papers, 2022). Necrosis or disintegration of skeletal muscle often followed by myoglobinuria. "First, PCSK9 inhibitors are alreadyrecognized in the guidelines as alternative therapy in patients with SAMS,including rhabdomyolysis-induced AKI." (PMID 39076187, 2022). "PCSK9 inhibitors are a guideline-recommended alternative LLT for patients withSAMS, including rhabdomyolysis-induced AKI." (PMID 39076187, 2022).
schizophrenia (2 papers, 2021 to 2022). A major psychotic disorder characterized by abnormalities in the perception or expression of reality. "Our findings suggest that PCSK9 might serve as a therapeutic target in schizophrenia patients with olanzapine-induced NAFLD." (PMID 35379885, 2022).
skin cancer (2 papers, 2023 to 2024). "PCSK9 proved playing oncogenic driving role in gastric, lung, colon, breast, liver, ovarian, and skin cancers, validating it as a novel molecular target in cancer." (PMID 36771126, 2023).
Xanthelasma (2 papers, 2021 to 2025). The presence of xanthomata in the skin of the eyelid. "Although limited in number, the PCSK9 variant appeared in a patient with CVD but without xanthelasma, which is consistent with the gene’s role in receptor turnover rather than lipid transport." (PMID 41398288, 2025).
abnormal glucose tolerance (1 paper, 2018). An abnormal resistance to glucose, i.e., a reduction in the ability to maintain glucose levels in the blood stream within normal limits following oral or intravenous administration of glucose. "Serum PCSK9 levels were significantly higher in subjects with abnormal glucose tolerance than in those with normal glucose tolerance (p < 0.01), and were also significantly higher in T2DM subjects than in IGR subjects (p < 0.01)." (PMID 29343301, 2018).
acne vulgaris (1 paper, 2024). "Our study suggests that alirocumab, a PCSK9 inhibitor, may reduce the risk of acne vulgaris." (PMID 38903813, 2024).
airway hyperresponsiveness (1 paper, 2024). "It is important to note that the improvement in airway hyperresponsiveness (AHR) observed after treatment with statins or anti-PCSK9 may be attributed to mechanical changes resulting from weight loss." (PMID 38762465, 2024).
alcoholic fatty liver disease (1 paper, 2023). Lipid infiltration of the hepatic parenchymal cells that is due to alcohol abuse. "A previously reported multivariable linear regression analysis indicated that non-alcoholic fatty liver disease (NAFLD) score levels were independently related to higher PCSK9 levels." (PMID 37466835, 2023).
alopecia (1 paper, 2025). Hair loss usually from the scalp. "Four patients (4.8%) switched back to PCSK9 inhibitors during follow-up due to adverse effects (alopecia, musculoskeletal manifestations, and injection site reactions)." (PMID 40648843, 2025).
anal carcinoma (1 paper, 2025). "Additionally, there was heterogeneity in the results for blood PCSK9 and anal cancer (p = 0.03) as well as anus cancer (p = 0.01)." (PMID 40443776, 2025).
apical periodontitis (1 paper, 2024). "PCSK9 deficiency significantly influences apical periodontitis." (PMID 39139638, 2024). "The expression of PCSK9 was increased in a mouse model of apical periodontitis induced by P. gingivalis and in the gingival tissues of patients with periodontitis." (PMID 39139638, 2024).
Ascites (1 paper, 2021). Accumulation of fluid in the peritoneal cavity (between the layers of the peritoneum that lines the abdomen). "Ascites volume and variceal size were not related to PCSK9 levels." (PMID 33461570, 2021).
Atherosclerotic lesion (1 paper, 2021). A lesion associated with atherosclerosis, a multifactorial and multipart progressive disease manifested by the focal development within the arterial wall of lesions, that ranges from the development of a fatty streak, plaque progression, and plaque disruption.
autoimmune liver diseases (1 paper, 2025). "Of clinical relevance, serum PCSK9 levels demonstrated diagnostic utility in distinguishing patients with autoimmune liver diseases from healthy controls." (PMID 41271978, 2025). "One of the most striking findings of this study is the diagnostic potential of serum PCSK9 levels in distinguishing patients with autoimmune liver diseases from healthy individuals." (PMID 41271978, 2025). "Though higher PCSK9 levels support the rationale for exploring anti-PCSK9 therapy as an option in patients with autoimmune liver diseases at risk for DILI, this warrants further preclinical and clinical investigations." (PMID 41271978, 2025). "Further studies are needed to confirm these results and to investigate the mechanistic role of PCSK9 in hepatic autoimmunity." (PMID 41271978, 2025). "The distribution of serum PCSK9 levels was assessed using the Shapiro-Wilk test, which revealed normal distribution exclusively in patients with autoimmune hepatitis (AIH) (p = 0.731)." (PMID 41271978, 2025). "This observational study was also unable to determine the role of increased serum PCSK9 levels in autoimmune liver disease." (PMID 41271978, 2025). "Here we investigated serum PCSK9 levels in patients with autoimmune liver diseases and compared them to healthy controls, with attention to sex-specific differences." (PMID 41271978, 2025). "Further functional studies are needed to clarify the role of PCSK9 in immune cell responses in autoimmune liver diseases." (PMID 41271978, 2025). "The AUROC for this group was 0.788 ± 0.039 (p < 0.001), and a serum PCSK9 level of 224 ng/ml exhibited a sensitivity of 92% and a specificity of 60% for diagnosing autoimmune liver disease." (PMID 41271978, 2025). "The AUROC was 0.788 ± 0.039 and a serum PCSK9 level of 224 ng/ml had a sensitivity of 92% and a specificity of 60% for diagnosing autoimmune liver disease." (PMID 41271978, 2025). "PCSK9 levels were significantly elevated in patients with autoimmune liver diseases compared to healthy controls (p < 0.001)." (PMID 41271978, 2025). "The AUROC was 0.755 ± 0.046 (p < 0.001) and a PCSK9 serum level of 224 ng/ml had 85% sensitivity and 59% specificity for diagnosing autoimmune liver disease." (PMID 41271978, 2025). "The AUROC was 0.755 ± 0.046 (p < 0.001), with a serum PCSK9 level of 224 ng/ml demonstrating a sensitivity of 85% and a specificity of 59% for diagnosing autoimmune liver disease." (PMID 41271978, 2025). "The AUROC was 0.788 ± 0.039 (p < 0.001) and a PCSK9 serum level of 224 ng/ml had a sensitivity of 92% and a specificity of 60% for diagnosing autoimmune liver disease." (PMID 41271978, 2025). "PCSK9 may serve as a biomarker in the diagnosis of autoimmune liver disease, even in patients with almost normal liver function test results." (PMID 41271978, 2025). "As novel immunomodulatory or anti-fibrotic therapies for autoimmune liver diseases are developed, monitoring PCSK9 dynamics could offer insight into treatment efficacy and disease activity." (PMID 41271978, 2025). "Notably, PCSK9 levels exhibited strong discriminatory power in identifying patients with autoimmune liver disease despite having almost normal liver parameters." (PMID 41271978, 2025). "This shows that serum PCSK9 levels increase even in patients with good liver function, suggesting that increased PCSK9 levels may indicate autoimmune liver disease." (PMID 41271978, 2025). "Importantly, PCSK9 showed good diagnostic performance, particularly in male patients with PSC and female patients with PBC, and may serve as a complementary biomarker in the diagnostic evaluation of autoimmune liver diseases." (PMID 41271978, 2025). "This study aimed to determine whether serum PCSK9 levels are increased in patients with the rare autoimmune liver diseases AIH, PBC, and PSC, and to assess whether PCSK9 levels are associated with disease severity, fibrosis stage, or sex." (PMID 41271978, 2025).
autoimmune liver diseases (continued). "Serum PCSK9 levels are elevated in both male and female patients with autoimmune liver diseases, independent of cholesterol levels or fibrosis stage." (PMID 41271978, 2025). "This study demonstrates that serum PCSK9 levels are significantly elevated in patients with autoimmune liver diseases—PSC, PBC, and AIH—regardless of disease severity, liver function parameters, or fibrosis stage." (PMID 41271978, 2025). "Interestingly, serum PCSK9 levels did not correlate with most of the conventional markers of liver injury, indicating that their elevation in autoimmune liver diseases is unlikely to result from hepatocellular damage alone." (PMID 41271978, 2025). "Serum PCSK9 levels were measured in 100 patients with autoimmune liver diseases — 57 with primary sclerosing cholangitis (PSC), 33 with primary biliary cholangitis (PBC), and 10 with autoimmune hepatitis (AIH)—and 88 healthy controls." (PMID 41271978, 2025).
carcinoma in situ of the (1 paper, 2024). "There are currently no reports on the role of PCSK9 in oral cavity and pharyngeal cancers or carcinoma in situ of the cervix uteri or endocervix." (PMID 38275613, 2024).
cerebral aneurysm (1 paper, 2021). "In our study, we found that the inhibition of genetically proxied LDL-C-lowering targets, PCSK9, might increase the risk of cerebral aneurysm." (PMID 34834523, 2021).
Chagas disease (1 paper, 2022). A parasitic infection caused by Trypanosoma cruzi. "All those genes are involved in biological process associated to Chagas disease: nervous system (LHX6, POU6F2, MDGA1, DISC1, PCSK9), immune system (ZMIZ, HLA-DRB1), Wnt pathway (DISC1), ion transport (KCNK15, PCSK9), striated muscles (SMYD3) or ATP metabolic process (ATP5S)." (PMID 36248819, 2022).
cholangitis (1 paper, 2023). An acute or chronic inflammatory process affecting the biliary tract. "Underlying diseases, such as pancreatitis and cholangitis, were, however, not related to altered systemic PCSK9 levels." (PMID 37515197, 2023).
coronary aneurysm (1 paper, 2025). Abnormal balloon- or sac-like dilatation in the wall of coronary vessels. "Similar to the findings in AAA, PCSK9 expression may also be elevated in coronary artery aneurysms, suggesting that PCSK9 inhibitors may play a role in the prevention or regression of atherosclerotic coronary artery aneurysms." (PMID 41247317, 2025).
cystic fibrosis (1 paper, 2025). Autosomal recessive disorder caused by pathogenic variants in the CFTR gene (cystic fibrosis transmembrane conductance regulator), which encodes a chloride and bicarbonate channel expressed in epithelial cells, and follow the diagnosis criteria. "For example, individuals carrying loss of function alleles in CFTR (leading to cystic fibrosis) or in PCSK9 (reducing LDL cholesterol and protecting against heart disease) may exhibit different sets of modifying loci than those relevant to individuals without the major effect variant." (PMID 41279859, 2025).
cystic kidney disease (1 paper, 2025). A congenital or acquired kidney disorder characterized by the presence of renal cysts. "Therefore, the aim of this study was to evaluate three lipid-lowering drug targets—HMGCR, PCSK9, and NPC1L1—was associated with a decreased risk of cystic kidney disease and PKD." (PMID 40289090, 2025). "Heterogeneity and pleiotropy test in the examined associations and weak instrument statistics between lipid phenotypes mediated by lipid-lowering drug targets (HMGCR, PCSK9, and NPC1L1) and cystic kidney disease and polycystic kidney disease." (PMID 40289090, 2025). "Forest plots showed the MR effect sizes of HMGCR-, PCSK9-, and NPC1L1-mediated LDL-C levels on cystic kidney disease and PKD." (PMID 40289090, 2025). "Indeed, the role of lipid-lowering agents, particularly PCSK9, and Niemann-Pick C1-like 1 (NPC1L1) inhibitors, in cystic kidney disease remains understudied." (PMID 40289090, 2025). "However, none of the genetic proxies for lipid-lowering drugs (PCSK9 and NPC1L1) targets were found to be causally associated with the risk of cystic kidney disease." (PMID 40289090, 2025). "Despite PCSK9 inhibitors effectively lowering LDL-C, our findings suggest that targeting PCSK9 alone may not sufficiently mitigate cystic kidney disease progression, possibly due to its limited role in renal-specific pathways." (PMID 40289090, 2025).
diabetic neuropathy (1 paper, 2025). A chronic, pathological complication associated with diabetes mellitus, where nerve damages are incurred due to diabetic microvascular injury involving small blood vessels that supply these nerves, resulting in peripheral and/or autonomic nerve dysfunction. "In addition, there was horizontal pleiotropy between PCSK9 and diabetic neuropathy (pEgger's⁣intercept = 0.040)." (PMID 40225015, 2025).
endometritis (1 paper, 2020). An acute or chronic, usually bacterial infectious process affecting the endometrium. "Interestingly, a subclinical dose of LPS induced PCSK9 upregulation (logFC = 1.60), which could have contributed to endometritis." (PMID 32545766, 2020).
esophageal tumors (1 paper, 2025). "Our analysis revealed increased PCSK6,PCSK9, MBTPS1, and FURINexpressions in human esophageal tumors." (PMID 40264581, 2025).
familial chylomicronemia syndrome (1 paper, 2021). A rare autosomal recessive disease characterized by the buildup in the blood of fat particles called chylomicrons (chylomicronemia), severe hypertriglyceridemia, and the risk of recurrent and potentially fatal pancreatitis and other complications. "This is particularly true for PCSK9 antibodies such as alirocumab and evolocumab or PCSK9 inhibitors based on siRNA technology such as inclisiran but is also true for drugs used in rare conditions such as volanesorsen in familial chylomicronemia syndrome." (PMID 34648074, 2021).
familial hypobetalipoproteinemia 1 (1 paper, 2021). Any hypobetalipoproteinemia in which the cause of the disease is a mutation in the APOB gene. "Gain-of-function gene variants of PCSK9 occur with familial combined hypercholesterolemia, in which individuals have increases in plasma total cholesterol, ApoB, and/or triglyceride levels, while loss-of-function variants occur with familial hypobetalipoproteinemia-1." (PMID 34504056, 2021).
focal epilepsy (1 paper, 2024). A seizure caused by a localized disorder. "However, some degree of heterogeneity emerged in the results concerning PCSK9-mediated LDL-C, encompassing both all types and focal epilepsy (excluding hippocampal sclerosis lesions)." (PMID 38523609, 2024).
fragile X syndrome (1 paper, 2021). A genetic syndrome caused by mutations in the FMR1 gene which is responsible for the expression of the fragile X mental retardation 1 protein. "For example, PCSK9 is important in regulation of lipoproteins and neuronal apoptosis and has abnormal function in individuals with fragile X syndrome." (PMID 34504056, 2021).
gastric tumor (1 paper, 2023). "The PCSK9 mRNA and protein levels recently proved elevated in gastric tumor patients’ tissues and sera versus healthy subjects." (PMID 37103355, 2023).
glomerulosclerosis (1 paper, 2022). A hardening of the kidney glomerulus caused by scarring of the blood vessels. "Heparin(oids) treatment did not influence serum total cholesterol (TC), plasma syndecan-1 and PCSK9 levels, creatinine clearance, proteinuria, glomerulosclerosis, and arterial neo-intima formation, 8 weeks after transplantation." (PMID 35345850, 2022).
glucose metabolism disorders (1 paper, 2016). "Both in vitro and in vivo studies revealed that polydatin ameliorates lipid and glucose metabolism disorders in a manner that is closely linked to PCSK9." (PMID 26833058, 2016).
gout (1 paper, 2024). A condition characterized by painful swelling of the joints, which is caused by deposition of urate crystals. "In conclusion, this research furnishes empirical evidence suggesting that HMGCR inhibitors elevate the risk of developing gout, while PCSK9 inhibitors heighten the risk of urate." (PMID 39926389, 2024). "The findings indicate that inhibitors targeting HMGCR may elevate the risk associated with the development of gout, while inhibitors targeting PCSK9 are likely to increase urate concentrations." (PMID 39926389, 2024). "Utilizing genetic instruments, our goal was to surmount the constraints inherent in observational studies and to furnish more robust evidence for the potential role of HMGCR, PCSK9, and NPC1L1 in the onset of gout and urate." (PMID 39926389, 2024). "In this investigation, the correlation between gene expression of HMGCR, PCSK9, and NPC1L1 and outcomes related to gout and urate was evaluated utilizing the SMR approach." (PMID 39926389, 2024). "In the current investigation, we employed a two-sample Mendelian Randomization analysis approach to explore the relationship between lipid-lowering agents (HMGCR inhibitors, PCSK9 inhibitors, and NPC1L1 inhibitors) and outcomes related to urate and gout." (PMID 39926389, 2024).